CRP (C-reactive protein)
Diseases named in the same sentence as CRP in open-access papers (continued):
Sharing a sentence is not in itself a finding about the gene and the disease.
esophageal cancer (continued). "Although these biomarkers, including CRP, CAR, GPS, PNI, and NLR, have shown prognostic value in various treatment settings for diverse cancers, including esophageal cancer, they have gained more attention recently with regard to immune-oncology treatment." (PMID 38717686, 2024). "Elevated CRP and a high NUn score on POD 4 provide high accuracy in predicting AL after esophageal cancer surgery." (PMID 38337519, 2024). "Serum PD‐L1 levels were positively correlated with neutrophil counts and CRP and SCC‐Ag levels and negatively correlated with albumin levels in patients with surgically treated esophageal cancer in this study." (PMID 31865635, 2020). "In the context of esophageal cancer surgery, CRP has been reported as a useful negative indicator for ruling out AL after esophagectomy." (PMID 37964057, 2023). "CRP on postoperative day 5 can be used as a marker to raise suspicion of anastomotic leakage in patients following an esophagectomy for esophageal cancer, but can especially be used as a negative predictor." (PMID 37103558, 2023). "CRP on postoperative day 5 can be used as a negative predictor for and can be used as a marker to raise suspicion of anastomotic leakage following esophagectomy for esophageal cancer." (PMID 37103558, 2023). "Recently, the modified GNRI (mGNRI) incorporating C-reactive protein (CRP), a well-known acute-phase reactant in inflammatory responses, instead of serum albumin was reported to be useful for the prediction of the early recurrence and prognosis in patients with esophageal cancer." (PMID 36096761, 2022). "Circulating factors such as C-reactive protein (CRP), soluble interleukin-6 receptor (sIL-6R) and vascular endothelial growth factor (VEGF) have demonstrated prognostic potential in esophageal cancer, however most studies to date have focused on squamous cell type esophageal tumors." (PMID 33202734, 2020).
liver dysfunction (68 papers, 2008 to 2026). "CRP was also significantly associated with liver dysfunction, although the effect size was small (OR 1.07; 95% CI: 1.00-1.14, p = 0.043)." (PMID 41673918, 2026). "The independent risk factors for SIH identified in this analysis included liver dysfunction, high uric acid, CRP > 5 mg, surgical time >5 h, norepinephrine use, and CPB > 3H." (PMID 41393261, 2025). "In MCS-treated patients, liver dysfunction was shown to be associated to the progressive release of inflammatory mediators, such as interleukin-6 (IL-6), IL-8, and C-reactive protein (CRP)." (PMID 25132729, 2014). "The decrease in CRP may be due to the liver dysfunction caused by HS." (PMID 36142577, 2022). "The logistic regression equation is as follows: −4.504 + (1.35 × Liver dysfunction) + (2.842 × High uric acid) + (2.016 × CRP > 5 mg) + (−1.682 × Surgical time >5H) + (2.486 × Norepinephrine use) + (2.506 × CPB >3H)." (PMID 41393261, 2025). "While TLC levels were within the normal range, elevated ALT and low CRP values suggested potential liver dysfunction." (PMID 41156578, 2025). "The neonate had recurrent inflammatory reactions with elevated C-reactive protein levels, severe cholestasis, a progressive liver dysfunction, and an increasingly distended abdomen with subsequent respiratory insufficiency." (PMID 40038796, 2025). "An impaired CRP response to E. coli bacteremia in patients with liver dysfunction has been shown before." (PMID 39997462, 2025). "Our study shows a significant inverse correlation between circulating levels of small HDL subclasses and key markers of oxidative stress and liver dysfunction, namely phenylalanine, tyrosine, bilirubin, and C-reactive protein." (PMID 40563298, 2025). "When interpreting CRP values, it is necessary to consider potential limitations (impairment of liver protein synthesis in severe hepatopathies and blocking of IL-6 during biological therapy—in both cases, CRP levels barely increase)." (PMID 38792824, 2024). "Initial blood tests revealed elevated C-reactive protein (CRP) and procalcitonin levels, liver dysfunction, and severe renal impairment likely due to dehydration from central diabetes insipidus." (PMID 39347295, 2024). "In some studies, IL-6 has been shown to be a more relevant prognostic factor in cases of severe systemic inflammation in patients with concomitant severe liver dysfunction than leukocyte count or CRP level." (PMID 37834802, 2023). "Recent studies have shown that high CRP levels have been observed in patients with liver dysfunction." (PMID 36899958, 2023). "She had lost approximately 3 kg in the past few months, had marked liver dysfunction, and an elevated level of C-reactive protein (CRP)." (PMID 33566306, 2021). "Blood examination showed significant liver dysfunction, markedly high C-reactive protein (CRP 19.1 mg/dL) and procalcitonin (48.3 ng/mL) levels." (PMID 33566306, 2021). "A 70-year-old Japanese man with complaints of abdominal bloating for 2 weeks along with liver dysfunction and elevated C-reactive protein (CRP) levels was referred to our hospital." (PMID 31771621, 2019). "In a study of Escherichia coli infection, the host capacity for CRP production was maintained in cirrhotic patients with severe liver dysfunction." (PMID 31821367, 2019). "AST and ALT represent liver dysfunction, and the levels of these enzymes were significantly higher; C-reactive protein is a biomarker of inflammation, and it was more elevated." (PMID 29343812, 2018). "In this patient, serum IL18 levels correlated well with serum ferritin levels and the extent of liver dysfunction but dissociated with serum CRP and IL6 levels which had remained normal after initial high-dose corticosteroids and cyclosporine therapy." (PMID 24455384, 2013). "Therefore, a large prospective study is warranted to investigate the potential influence of CRP on the efficacy of VRZ in patients with liver dysfunction." (PMID 38239188, 2023).
liver dysfunction (continued). "The hepatic oxidative stress and fibrosis that damaged the ewe’s liver cells seriously and liver dysfunction for malnourished pregnant ewe might restraint the synthesis of CRP." (PMID 30056659, 2019). "Studies have confirmed that severe IRI during LT causes significant postoperative changes in lab results, especially CRP and ALB, affected by liver dysfunction and stress." (PMID 40705850, 2025). "Markers such as total bilirubin, troponin-I, C-reactive protein (CRP), and lactate dehydrogenase (LDH) were markedly elevated, indicating liver dysfunction, myocardial injury, and systemic inflammation." (PMID 39371874, 2024). "The incidence of liver dysfunction was 0% in patients with no risk factors, 10.7% in those with elevated ALT only, 8.3% in those with elevated CRP only, and 50% in those with both elevated ALT and CRP." (PMID 41673918, 2026). "Furthermore, the prognostic significance of an inflammatory marker, C-reactive protein (CRP), and the liver dysfunction marker, albumin–bilirubin (ALBI) score have been reported for eribulin-treated patients." (PMID 39979692, 2025). "Interestingly, there were moderate correlations between fT3 and parameters of liver dysfunction (MELD: ρ = -0.448; p <0.001; and albumin: ρ = 0.434; p <0.001) and systemic inflammation (IL-6: ρ = -0.496; p <0.001; and CRP: ρ = -0.356; p <0.001)." (PMID 38125301, 2024). "Higher levels of WBC, CRP, ALT, CK-MB, INR, and lower levels of hemoglobin, PLT were found in the non-survivor group than survivor group (all P < 0.001), which indicated severe inflammation, liver dysfunction, heart insufficiency, and poor coagulation." (PMID 36539725, 2022). "The correlations of lipid profile indicators (triglyceride, cholesterol, HDL-C and LDL-C) with liver function biomarkers (INR, bilirubin, albumin, CRP, platelet, AST/ALT ratio) and liver dysfunction scoring results (CTP score and MELD score) were assessed by Pearson χ2 test." (PMID 30927926, 2019). "Lastly, the relationship between CRP/ALB ratio and liver dysfunction could be an important issue for prognosis in postoperative ICU patients in our study." (PMID 29495423, 2018). "High levels of C-reactive protein (CRP) have been found in patients with alcoholic cirrhosis without infections that correlate with liver dysfunction and mortality." (PMID 27359339, 2016). "However, we observed a significant correlation between preoperative CXCL10 levels and laboratory parameters of liver dysfunction (AST: Rs = 0.304, p = 0.001; bilirubin: Rs = 0.370, p = 0.001; ALP: Rs = 0.286, p = 0.002) as well as between baseline CXCL13 levels and CRP (Rs = 0.344, p = 0.001)." (PMID 36077611, 2022). "Blood tests showed liver dysfunction (aspartate aminotransferase, 404 U/L; alanine aminotransferase, 418 U/L; lactate dehydrogenase, 919 U/L; alkaline phosphatase, 331 U/L; gamma-glutamyl transpeptidase, 86 U/L) and inflammatory status (white blood cells [WBC]: 11,400/μL, CRP: 19.1 mg/dL)." (PMID 33566306, 2021).
Hepatitis (67 papers, 2008 to 2026). Inflammation of the liver. "High CRP levels and risk of chronicity: Persistently high CRP levels suggest uncontrolled inflammation, which increases the risk of hepatitis becoming chronic and transitioning into liver fibrosis." (PMID 39996800, 2025). "This study is consistent with previous findings on LPS-induced liver inflammation, confirming that LPS produces a potent inflammatory response that causes the elevation of CRP, IL-1β, and TNF-α." (PMID 39727984, 2024). "These inflammatory cytokines, such as TNF-α, IL-6, and C-reactive protein, can induce liver inflammation and fibrosis, causing liver cell damage and interfering with liver function." (PMID 38076231, 2023). "Furthermore, delivery of increased levels of the tumor necrosis factor-α and interleukin-6 to the liver may cause liver inflammation and contribute to elevated production of C-reactive protein (CRP)." (PMID 33603787, 2021). "Treatment of EpCAM positive tumor patients with catumaxomab caused dose dependent hepatitis as evidenced by significant elevations in serum alanine- and aspartate aminotransferases, bilirubin, γGT and induction of the acute phase C-reactive protein (CRP) and the cytokines IL6 and IL8." (PMID 27058902, 2016). "CRP as an indicator of hepatitis progression: A rapid increase in CRP levels can be used as a real-time indicator of inflammatory activity." (PMID 39996800, 2025). "The lower expression level of CRP in the liver of all the treatment groups suggests reduced systemic infection and liver inflammation." (PMID 35862957, 2022). "The white cell count remained normal while the CRP rose to 256 mg/L and she had a mild hepatitis (ALT 87 U/L)." (PMID 30270856, 2016). "We performed multiple logistic regression analysis using age, BMI, ALT, CRP, and sCD14, which were significantly higher in patients with severe liver inflammation compared with patients with mild inflammation in univariate analyses." (PMID 23762319, 2013). "A previous report indicated that CRP is a non-invasive marker of alcoholic hepatitis in heavy drinkers compared to hepatitis unrelated to alcohol." (PMID 21806828, 2011). "Hepatitis screen (hepatitis B and C), liver function tests, serum protein electrophoresis, C-reactive protein (CRP) and all his other blood results were normal." (PMID 18851753, 2008). "Therefore, CRP measurement plays an important role in the early diagnosis of LPS-induced hepatitis and monitoring therapeutic efficacy." (PMID 39996800, 2025). "we selected four patients who experienced G4 irAEs that lasted >1 week; of these patients, two had skin toxicities and two had hepatitis, results suggested that the changes in CRP, IL-6, and lymphocyte subsets were found to be consistent with the severity of irAEs over time." (PMID 35756643, 2022). "Liver inflammation was determined by serum levels of C-reactive protein (CRP)." (PMID 32155178, 2020). "A retrospective study found that CRP was increased in patients with irAEs, such as pituitary inflammation, hepatitis, thyroiditis and autoimmune colitis (upper limit of normal (ULN) 5 mg/L), but elevated CRP levels did not correlate with the severity of organ damage." (PMID 33317597, 2020). "At this stage the CRP was normal but he had mild residual hepatitis (ALT 103 U/L)." (PMID 30270856, 2016). "Despise the presence of hepatitis, hs-CRP still acted as a reliable indicator for prognosis." (PMID 25874450, 2015). "It is important to mention that development of hepatic IR impairs insulin response in the hepatocytes, which results in the inhibition of glycogen synthesis and the increase in hepatic gluconeogenesis, lipogenesis, and synthesis of proinflammatory proteins such as C-reactive protein (CRP)." (PMID 35011414, 2021). "The level of CRP is correlated with the infection progress and could be considered as a disease progression prognostic factor in many types of hepatitis virus infection in human, including hepatitis A, B, and C." (PMID 23923051, 2013).
Hepatitis (continued). "The results of the Bayesian network model indicate that DOI, AT3, SCC, CRP, and TC have a direct connection with the occurrence of hepatic malignancy; Gender, FT4, hepatitis type, and Ca indirectly influence the development of hepatic malignancy." (PMID 41602421, 2026). "C-reactive protein (CRP) is an acute-phase protein synthesized by hepatocytes in response to inflammatory stimuli and is highly sensitive to liver inflammation in NAFLD." (PMID 40951433, 2025). "Studies have shown that such diets elevate inflammatory markers like C-reactive protein (CRP) and interleukin-6 (IL-6), contributing to vascular damage, arterial stiffness, and worsening liver inflammation and fibrosis, thereby accelerating MASLD progression." (PMID 40242166, 2025). "A retrospective study reported increased circulating levels of C-reactive protein (CRP) in patients with ICI-induced pituitary inflammation, hepatitis, thyroiditis and autoimmune colitis." (PMID 34790123, 2021). "This suggests that antiviral therapy influences the expected capacity of the CRP/ALB ratio, which should be confirmed in future studies investigating the dose and timing of antiviral therapy in other types of hepatitis." (PMID 31821367, 2019). "The relationship between hepatitis C virus (HCV) infection and C-reactive protein (CRP), which is an inflammatory biomarker, is limited in studies with the general population." (PMID 30813467, 2019). "Specifically, upon drug administration all patients developed dose dependent hepatitis of different grades with significant serum elevations in ALT, AST, bilirubin and CRP." (PMID 27058902, 2016). "Liver function:ALT:353U/L, AST:1095U/L, T-BIL:33.3μmol/L,Creatinine(CRE):43umol/L(normal:58-110umol/L), procalcitonin (PCT): 6.68 ng/ml(normal:0-0.5ng/ml), C-reactive protein(CRP): 104.68 mg/L(normal:0-6mg/L), which was suggestive of immune checkpoint inhibitor-related hepatitis." (PMID 41459532, 2025). "Currently, inflammatory markers such as CRP, IL-1β, and TNF-α are widely used to evaluate hepatitis, but these markers may lack specificity." (PMID 39996800, 2025). "C-reactive protein (CRP), as an acute phase protein, is a sensitive index to evaluate the systemic inflammatory response, and its increase in MASLD patients may indicate the presence of liver inflammation." (PMID 41480537, 2025).
Nephropathy (67 papers, 2012 to 2026). A nonspecific term referring to disease or damage of the kidneys. "Microalbuminuria was substantially aggravated in adult SHR-CRP rats as compared with young animals, which is in accordance with the established phase of the incipient nephropathy associated with transgenic CRP expression at the age of one year." (PMID 36140169, 2022). "Inflammation and metabolic imbalance may cause kidney damage, and the C-reactive protein-triglyceride glucose index (CTI) represents both factors." (PMID 42051350, 2026). "Moreover, reduction of serum CRP was observed after losartan was administered for 28 days to patients who had interstitial inflammation and fibrosis associated with chronic cyclosporine-induced nephropathy." (PMID 22583484, 2012). "This study examined the association between atherogenic (IA), thrombogenic (IT), and lipophilic (LT) indices—as fat intake indicators—and the risk of nephropathy in T2DM patients, after adjusting for glycemic index, lipid profile, and CRP levels." (PMID 40041714, 2025). "The CRP/albumin (CAR) ratio has also been associated with inflammation and nephropathy in diabetic patients." (PMID 37370958, 2023). "She exhibited fever, strawberry-like rash, hypotension requiring vasopressors, decreased ejection fraction, nephropathy, and significant elevations in her CRP and d-dimer." (PMID 35241158, 2022). "A positive correlation between CRP levels and lung lesions, kidney damage, and cardiac injury has been demonstrated; when the inflammation or tissue damage is resolved, CRP concentration falls." (PMID 33244379, 2020). "Systemic inflammatory indexes including NLR, PLR, and CRP have been introduced to as a significant independent marker for prediction of adverse outcome in oncologic disorders, cardiovascular diseases, and nephropathy." (PMID 31827921, 2019). "Three inflammatory mediators in particular: interleukin 6 (IL-6), tumor necrosis factor α (TNF-α), and C-reactive protein (CRP), when combined in a z-score, are associated with development of retinopathy, nephropathy and cardiovascular disease in diabetics." (PMID 29075511, 2017). "However, the lack of complementary kidney function assessments (e.g., eGFR and imaging) and inflammatory markers (e.g., CRP and IL-6) limits our ability to definitively attribute these findings to nephropathy or systemic inflammation." (PMID 40177219, 2025). "Increased TC was associated with kidney damage 24-h PRO, PRO, ACR, and the inflammatory marker CRP." (PMID 39877363, 2024). "Previous studies have shown that CRP can be involved in inflammation and kidney damage." (PMID 37102663, 2023). "Even after adjustment for all variables correlated with NLR in the previous analyses (age, CVD, duration of CVD, serum albumin, CRP, eGFR, calcium, parathormone, central DBP, cause of nephropathy, ESA), dp-ucMGP, mean BP and gender were strong, independent predictors of NLR." (PMID 36837922, 2023). "IL-6 and cystatin-C, as markers of inflammation and kidney damage, respectively, are likely to provide insight into prediction of risk for CKD outcomes after AKI, as our feasibility data suggest that IL-6 is a more sensitive than high sensitivity-CRP." (PMID 30898807, 2019). "An ongoing inflammatory process demonstrating a direct correlation of C-reactive protein (CRP) with urinary miR-21a is speculated to play a role in kidney damage." (PMID 30347712, 2018). "We analyzed whether treatment with dexamethasone reduced the risk of scarring in specific high-risk patients, and the obtained ORs were not significant for these subgroups (i.e., age older 2 years, prolonged fever, VUR, elevated CRP, or magnitude of kidney damage in DMSA)." (PMID 35041042, 2022). "The concentration of CRP may progressively rise due to chronic inflammation and cytokines activation in both T2DM and GDM patients that may be extended to diabetic angiopathy, vessel damage and nephropathy caused by concomitant endocrine disturbances." (PMID 32326243, 2020).